HTR3C (5-hydroxytryptamine receptor 3C)
Description:
Forms serotonin (5-hydroxytryptamine/5-HT3)-activated cation-selective channel complexes, which when activated cause fast, depolarizing responses in neurons.
Tractability: Small molecule: an approved drug acts on it; a high-quality ligand is known; it belongs to a druggable protein family. Antibody: UniProt places it where antibodies can reach, with high confidence; its Gene Ontology location is reachable by antibodies, with high confidence; UniProt predicts a signal peptide or a membrane-spanning region. PROTAC: a small molecule that binds it is known.
Gene: Protein-coding gene on chromosome 3 (184,053,047 to 184,060,673, forward strand). Ensembl gene ENSG00000178084.
Subcellular location: Postsynaptic cell membrane; Cell membrane
Pathways (Reactome):
Neuronal System: Neurotransmitter receptors and postsynaptic signal transmission
Gene Ontology:
Molecular function: protein binding; serotonin-gated monoatomic cation channel activity; extracellular ligand-gated monoatomic ion channel activity; monoatomic ion channel activity; transmembrane signaling receptor activity
Biological process: serotonin receptor signaling pathway; serotonin-gated cation-selective signaling pathway; transmembrane transport; calcium ion transport; monoatomic ion transmembrane transport; monoatomic ion transport
Cellular component: plasma membrane; serotonin-activated cation-selective channel complex; neuron projection; synapse; transmembrane transporter complex; membrane; postsynaptic membrane
Genetic constraint (gnomAD): Loss-of-function variants: 24 observed, 28.95 expected, observed/expected ratio (o/e) 0.83, 90% interval 0.6 to 1.17. The upper end of that interval is the gene's LOEUF score, 1.17, which puts it in group 5 of 6, group 1 being the genes least tolerant of losing a copy. Missense variants: 472 observed, 512.37 expected, observed/expected ratio (o/e) 0.92, 90% interval 0.85 to 0.99. Synonymous variants: 186 observed, 198.14 expected, observed/expected ratio (o/e) 0.94, 90% interval 0.83 to 1.06.
Homologues: Orthologues: chimpanzee HTR3C (99% identical), macaque HTR3C (85% identical), dog HTR3C (82% identical), pig HTR3C (80% identical). Paralogues in human: HTR3E (74% identical), HTR3D (49% identical), HTR3A (34% identical), HTR3B (27% identical), CHRNA7 (22% identical), CHRNA4 (22% identical), CHRNA6 (22% identical), CHRNA2 (22% identical), CHRNA3 (22% identical), CHRNB4 (21% identical), CHRNB3 (21% identical), CHRND (21% identical), and 33 more.
Diseases named in the same sentence as HTR3C in open-access papers:
HTR3C is named in the same sentence as 8 diseases in open-access papers, as found by Europe PMC text mining. Sharing a sentence is not in itself a finding about the gene and the disease. The quoted sentences say what the papers report.
Barrett's oesophagus (1 paper, 2016). "To our knowledge, we have identified for the first time an oesophageal adenocarcinoma association near the HTR3C and ABCC5 genes that is not observed in Barrett's oesophagus." (PMID 27527254, 2016).
lung carcinoma (1 paper, 2021). "In this study, we found that HTR3C was amplified with high frequency in lung cancer patients, and HTR3C protein expression levels were significantly associated with lymph node metastasis and distant metastasis in lung cancer tissues." (PMID 34868311, 2021). "Based on the IHC results, high protein expression levels of HTR3C were associated with lymph node metastasis, distant metastasis, and recurrence in lung cancer patients." (PMID 34868311, 2021). "Moreover, lung cancer patients presenting with high HTR3C protein levels were associated with shorter OS and DFS than patients with low HTR3C protein levels." (PMID 34868311, 2021). "Taken together, these data demonstrated that HTR3C expression levels were associated with poor DFS and OS in lung cancer patients, indicating that HTR3C can serve as a useful predictive biomarker for lung cancer." (PMID 34868311, 2021). "In the BioGRID dataset, HTR3C interaction with the oncogene IMPAD1 was shown to promote lung cancer metastasis via the inhibition of mitochondrial electron transport." (PMID 34868311, 2021). "To evaluate HTR3C protein levels in lung cancer, we examined the expression of HTR3C in primary lung tumors from 128 patients using IHC and correlated HTR3C expression with the clinicopathological characteristics of patients." (PMID 34868311, 2021). "High levels of HTR3C protein expression were correlated with shorter OS and DFS compared with low levels of HTR3C protein expression, and Cox regression analyses demonstrated that HTR3C expression levels could serve as an independent prognostic factor for lung cancer outcomes." (PMID 34868311, 2021). "In this study, HTR3 family members were assessed in NSCLC patients, which showed that HTR3C, HTR3D, and HTR3E were amplified with high frequency among lung cancer patients." (PMID 34868311, 2021). "We could not exclude the possibility that HTR3C amplification or expression may also be correlated with the response rate to ICB; however, this is the first study to evaluate alterations in the HTR3C gene and protein expression in lung cancer patients." (PMID 34868311, 2021).
tumor (3 papers, 2021 to 2024). "Second, an immune-related gene prognostic signature were established via regression analysis, including 2 oncogenic genes (AGTR1, HTR3C) and 2 tumor suppressor genes (SERPIND1 and CD3E)." (PMID 38355782, 2024). "Through univariate Cox regression analysis, nine genes, including 3 oncogenes (HTR3C, CRHR2 and AGTR1), 6 tumor suppressor genes (CD8A, CD3E, SERPIND1, CXCR6, BMX and CD247) were proved to be correlated with the overall survival of EC patients." (PMID 38355782, 2024).
HTR3C also shares sentences with these, for which no sentence is quoted: breast carcinoma (1 paper); cancer (1); irritable bowel syndrome (1); lymph node metastasis (1); oesophageal adenocarcinoma (1).